DAP (death associated protein)
Description:
Ribosome-binding protein involved in ribosome hibernation, a process during which ribosomes are stabilized in an inactive state and preserved from proteasomal degradation (By similarity). Acts via its association with eiF5a (EIF5A and EIF5A2) at the polypeptide exit tunnel of the ribosome, preventing mRNA translation (By similarity). Involved in ribosome hibernation in the mature oocyte by preventing mRNA translation, leading to ribosome inactivation (By similarity). Ribosomes, which are produced in large quantities during oogenesis, are stored and translationally repressed in the oocyte and early embryo (By similarity). Also acts as a negative regulator of autophagy. Involved in mediating interferon-gamma-induced cell death.
Synonyms: DAP1
Tractability: PROTAC: ubiquitination databases record sites on it.
Gene: Protein-coding gene on chromosome 5 (10,679,230 to 10,761,273, reverse strand). Ensembl gene ENSG00000112977.
Subcellular location (Human Protein Atlas): Mitochondria; Vesicles; Nucleoplasm
Gene Ontology:
Molecular function: ribosome binding
Biological process: apoptotic process; apoptotic signaling pathway; negative regulation of autophagy; ribosome hibernation
Genetic constraint (gnomAD): Loss-of-function variants: 8 observed, 11.18 expected, observed/expected ratio (o/e) 0.72, 90% interval 0.42 to 1.29. The upper end of that interval is the gene's LOEUF score, 1.29, which puts it in group 5 of 6, group 1 being the genes least tolerant of losing a copy. Missense variants: 89 observed, 104.31 expected, observed/expected ratio (o/e) 0.85, 90% interval 0.72 to 1.02. Synonymous variants: 35 observed, 37.59 expected, observed/expected ratio (o/e) 0.93, 90% interval 0.71 to 1.24.
Homologues: Orthologues: mouse Dap (96% identical), pig DAP (95% identical), guinea pig Dap (92% identical), rat Dap (92% identical), tropical clawed frog dap (73% identical), dog DAP (71% identical), chimpanzee DAP (64% identical), zebrafish dap (63% identical), Drosophila melanogaster CG12384 (43% identical), Caenorhabditis elegans F54B8.4 (25% identical), Caenorhabditis elegans T28F4.5 (25% identical). Paralogues in human: DAPL1 (34% identical).
Diseases named in the same sentence as DAP in open-access papers:
DAP is named in the same sentence as 21 diseases in open-access papers, as found by Europe PMC text mining. Sharing a sentence is not in itself a finding about the gene and the disease. The quoted sentences say what the papers report.
ciliopathies (1 paper, 2016). "Consistent with a DAP role in ciliogenesis is the evidence that mutations in DAP proteins such as C2cd3, Cep83, Cep164, and SCLT1 result in ciliopathies." (PMID 26981235, 2016).
COVID-19 (1 paper, 2024). A disease caused by infection with severe acute respiratory syndrome coronavirus 2. "In the validation set (GSE190496), we observed a significant increase in the gene expression levels of LSS, HYOU1, ACADVL, PRKAB2, PLIN2, AUP1, and DAP in the COVID-19 group compared to the control group." (PMID 38932215, 2024). "In sum, this study identifies seven lipophagy-related genes (ACADVL, HYOU1, DAP, AUP1, PRXAB2, LSS, and PLIN2) as biomarkers and potential therapeutic targets for COVID-19." (PMID 38932215, 2024). "Seven lipophagy-related genes, including ACADVL, HYOU1, DAP, AUP1, PRXAB2, LSS, and PLIN2, were used as biomarkers and drug targets for COVID-19." (PMID 38932215, 2024). "The lipophagy-related genes ACADVL, HYOU1, DAP, AUP1, PRXAB2, LSS, and PLIN2 can be used as biomarkers and drug targets for COVID-19." (PMID 38932215, 2024).
Crohn disease (1 paper, 2011). A gastrointestinal disorder characterized by chronic inflammation involving all layers of the intestinal wall, noncaseating granulomas affecting the intestinal wall and regional lymph nodes, and transmural fibrosis. "Death associated protein (DAP or DAP1) has been linked with ulcerative colitis rather than Crohn’s disease, and encodes a ubiquitously expressed protein originally identified in a screen for factors involved in IFNγ-induced apoptosis." (PMID 21994779, 2011).
cystic kidney (1 paper, 2022). "Although some of the defects, such as cardiac looping, holoprosencephaly, polydactyly, and cystic kidney are common in major ciliary gene mutations, such as Kif3a or Ift88, the phenotypic spectrums of the mouse models for DAP genes are diverse." (PMID 36407107, 2022).
leiomyoma (1 paper, 2013). A well-circumscribed benign smooth muscle neoplasm characterized by the presence of spindle cells with cigar-shaped nuclei, interlacing fascicles, and a whorled pattern. "By contrast, the expression of several tumor suppressor genes [comprising death-associated protein (DAP), phosphatase and tensin homolog (PTEN) and Ras association (RalGDS/AF-6) domain family member 1 (RASSF1A)] was downregulated in leiomyosarcoma specimens compared to leiomyoma." (PMID 24649216, 2013).
muscular dystrophies (1 paper, 2020). "The most severe muscular dystrophy is caused by mutations in dystrophin-associated-proteins (DAP, also called dystrophin–glycoprotein complex (DGC)) on the plasma membrane, although various mutations in different proteins cause human muscular dystrophies." (PMID 32244622, 2020).
cancer (3 papers, 2016 to 2022). A tumor composed of atypical neoplastic, often pleomorphic cells that invade other tissues. "Splice variants related to four genes (DBNDD2, DAP, ITPK1, and ROGDI) previously reported upregulated in breast/other human cancers were found downregulated in AKT1 silenced samples compared to control (siNoN)." (PMID 35892586, 2022). "Second, different proteoforms from the same cancer-related gene (e.g., DAP, CALM1, HDGF, JPT1, RALY, and NPM1) may have potentially varied biological functions in modulating CRC metastasis, because they show opposite expression profiles between the SW480 and SW620 cells." (PMID 36542699, 2022). "In this study, we used telomerase-positive cancer cells (HTC75) to discover the mechanism of the telomerase-ALT switch by inducing telomere-specific DNA damage, alpha-thalassemia X-linked syndrome protein (ATRX) knockdown and deletion of death associated protein (DAXX)." (PMID 27578458, 2016).
tumor (3 papers, 2001 to 2022). "Dlk/ZIP kinase is a member of the Death Associated Protein (DAP) kinase family of pro-apoptotic serine/threonine kinases that have been implicated in regulation of apoptosis and tumour suppression." (PMID 11742505, 2001).
DAP also shares sentences with these, for which no sentence is quoted: amyotrophic lateral sclerosis (1 paper); cervical cancer (1); diabetes (1); frontotemporal dementia (1); glioblastoma multiforme (1); holoprosencephaly (1); infection (1); leiomyosarcoma (1); prostate carcinoma (1); systemic lupus erythematosus (1); thalassemia (1); ulcerative colitis (1); viral infection (1).